INS (insulin)
Diseases named in the same sentence as INS in open-access papers (continued):
Sharing a sentence is not in itself a finding about the gene and the disease.
Insulin resistance (continued). "Another study fed mice with a diet providing 38.5% of energy as sucrose and observed elevated plasma glucose levels in the early phase of an oral glucose tolerance test (OGTT) indicative of insulin resistance or impaired insulin release." (PMID 27882410, 2016). "It is a metabolic disorder characterized by hyperglycemia due to defective insulin secretion or insulin resistance." (PMID 27847406, 2016). "On this final point, there is a large literature primarily originating from high-income countries relating to the fear of insulin, or “psychological insulin resistance”." (PMID 27583362, 2016). "In accordance with BAT insulin resistance, insulin-induced Akt phosphorylation was strongly decreased in Bscl2−/− BAT." (PMID 27748422, 2016). "This glucose intolerance was present despite a tendency toward increased insulin release, as calculated using AUCs over 60 minutes, suggesting the presence of insulin resistance in peripheral tissues." (PMID 27618559, 2016). "There are multiple mechanisms for decreased insulin sensitivity or insulin resistance, and one of them is related with visceral adiposity." (PMID 27274905, 2016). "IGFBP7 binds to insulin and thereafter inhibits the binding of insulin to IR, impairing the subsequent signaling, which at least in part leads to the pathological state of insulin resistance and hyperinsulinemia." (PMID 27101796, 2016). "Taken together, our data suggest that the decrease in miR-194 expression observed in insulin resistant muscle is an adaptive response to facilitate tissue glucose uptake and metabolism in the face of insulin resistance." (PMID 27163678, 2016). "The primary etiology in T2DM is the development of insulin resistance, or the pathological decline in insulin response in peripheral tissues." (PMID 27438860, 2016). "We referred to the literature to parametrise our model for insulin resistance and took account of the fact that tissues are affected by insulin resistance to different degrees." (PMID 27306890, 2016). "BMI was included in our stepwise multiple regression model to predict both fasting insulin and insulin resistance." (PMID 27824069, 2016). "RMSSD was, on average, 26 % lower in men with higher fasting insulin and 29 % lower in men with lower insulin resistance; for women, the corresponding estimates were smaller at 4 and 9 %, respectively." (PMID 26983644, 2016). "HL-IGR patients in our study have higher insulin values compared with HL-NGR-patients reflecting more pronounced insulin resistance." (PMID 26762550, 2016). "We have provided evidences that miR-135 directly induces insulin resistance in C2C12 cell line by targeting the insulin signaling pathway." (PMID 27602317, 2016). "Intra- and intermuscular adipose tissue (IMAT) likely contributes to insulin resistance through local secretion of pro-inflammatory adipokines and impaired insulin signalling in muscle." (PMID 27916865, 2016). "The results of this study differ from the results of an earlier study that showed greater insulin resistance, impaired glucose tolerance, and lower insulin response to a glucose challenge in Mg-restricted rats." (PMID 27136580, 2016). "Insulin resistance assessed by homeostasis model assessment of insulin resistance and quantitative insulin sensitivity check index were also dose-dependently improved with OFS treatment." (PMID 27941667, 2016). "This is likely to be a result of the development of insulin resistance through chronic insulin treatment, which has been described previously." (PMID 26592777, 2016). "This insulin-stimulated translocation of GLUT4 from intracellular sites to the plasma membrane is defective in individuals with insulin resistance and T2DM thus providing an impetus to comprehend how this trafficking pathway is controlled." (PMID 27795741, 2016). "When supplied exogenously or overexpressed as a transgene, adiponectin suffices to promote insulin action and ameliorates insulin resistance." (PMID 26993044, 2016).
Insulin resistance (continued). "Our results show that defenestration associated with old age and P407 interferes with the insulin transfer and uptake in the liver and impairs hepatic insulin signaling with systemic implications for glucose tolerance and insulin resistance." (PMID 27095270, 2016). "To elucidate the potential mechanism underlying the observed ASP-mediated improvement in hyperglycemia and insulin resistance, we evaluated intracellular insulin signaling pathway molecules in the liver." (PMID 27189109, 2016). "Most patients with NAFLD have normal fasting glucose concentrations, but high levels of fasting insulin and high hepatic insulin resistance." (PMID 27973438, 2016). "We observed a significant positive correlation between circulating periostin levels and fasting plasma insulin, and insulin resistance assessed by HOMA-IR in overweight and obese individuals, but not in normal weight participants." (PMID 27885258, 2016). "Taking these results together, p38α MAPK mediates the effect of chronic insulin to promote insulin resistance by suppressing IRS1 and IRS2." (PMID 27376265, 2016). "The two metabolic defects that characterize T2DM are a decrease response of peripheral tissue to insulin (insulin resistance) and failure of insulin secretion by pancreatic β-cells." (PMID 27298517, 2016). "Similar to NO dysfunctional effects in MetS, it has been shown that obese DM subjects blunted insulin's antiplatelet effects, confirming that human platelets can undergo insulin resistance." (PMID 28053690, 2016). "It is known that some of the named metabolic disturbances in childhood obesity are related to increased insulin blood levels and insulin resistance." (PMID 27066273, 2016). "Ceramide seems to induce insulin resistance by inhibiting insulin signal transduction, principally at Akt." (PMID 26788518, 2016). "Insulin, a physiological inhibitor of autophagy, is commonly increased within NAFLD mainly caused by insulin resistance." (PMID 27104558, 2016). "Mean (±SEM) fasting concentrations of plasma lipids and lipoprotein concentrations, glucose, insulin, markers of insulin resistance, and inflammatory markers at baseline, during and following ingestion of WGO and NWG." (PMID 27872611, 2016). "Insulin resistance can be defined as the inability of insulin to stimulate glucose disposal, and when an insulin-resistant individual is unable to secrete sufficient insulin to overcome this defect, T2D develops." (PMID 27312935, 2016). "TNFα depletion in ob/ob genetic or diet-induced obese mice reduces insulin resistance and improves insulin signaling in adipose tissue and muscle." (PMID 28025491, 2016). "In particular, skeletal muscle is responsible for the major portion of insulin-stimulated whole body glucose disposal and hence it plays important roles in the pathogenesis of insulin resistance." (PMID 27388225, 2016). "Glucose, insulin, adiponectin, leptin, and insulin resistance (IR) index were measured on days 1 and 12 after the onset of MI." (PMID 26989445, 2016). "Aged APN-KO mice developed hippocampal insulin resistance with reduced pAkt induction upon intracerebral insulin injection." (PMID 27884163, 2016). "Evaluation of the effects of insulin levels on these systems also indicated that hyperglycemic conditions led to insulin resistance over time." (PMID 28649179, 2016). "This study demonstrated that gender, BMI and WC are simple predictors of fasting insulin and insulin resistance in overweight/obese adolescents." (PMID 27824069, 2016). "Inflammation resulting from the increased pro-inflammatory cell environment disrupts insulin action and produces insulin resistance and β-cell dysfunction." (PMID 29051427, 2016). "The effect on ethnic differences in fasting insulin and insulin resistance (based on comparisons with white Europeans) of adjusting for dietary intakes of fruit, vegetables and vitamin C and plasma vitamin C concentrations were examined." (PMID 26498636, 2016).
Insulin resistance (continued). "As insulin resistance can be developed in the presence of inflammation or as a result of alterations in counter regulatory hormones that affect insulin." (PMID 27148410, 2016). "Susceptibility to type 2 diabetes (T2D), a disorder characterized by chronic hyperglycemia in the context of inadequate insulin secretion and peripheral tissue insulin resistance, is influenced by inheritance with superimposed dietary and lifestyle factors." (PMID 27383215, 2016). "Another study showed that metformin was more effective in reducing testosterone levels but rosiglitazone had a better effect on decreasing serum insulin and insulin resistance." (PMID 28331909, 2016). "Protection against insulin resistance by an alternating diet was also confirmed using an insulin tolerance test (ITT)." (PMID 27189661, 2016). "These pathological mechanisms mediate a reduction in insulin-stimulated glucose uptake leading to insulin resistance." (PMID 27894336, 2016). "It is known that obesity is a major contributor to insulin resistance and changes in adiposity can greatly alter insulin sensitivity." (PMID 27916833, 2016). "Because insulin resistance affects all tissues in the body, it is a challenge to identify the signals that promote islet growth in insulin-resistant states." (PMID 27562101, 2016). "Our study in iPS cells demonstrates an important role for insulin resistance as a driver of mitochondrial oxidative dysfunction, even prior to differentiation of cells into more classical insulin target tissue cell types, such as muscle, fat and liver." (PMID 26948272, 2016). "The present data suggest that WNT3a and WNT4 are important components of crosstalk between insulin-resistant tissues and the pancreas in maintaining β-cell adaptation to systemic insulin resistance." (PMID 27527335, 2016). "Irisin has been suggested to increase total energy expenditure, improve glucose tolerance and reduce fasting insulin, therefore induce improvement of glucose homeostasis, insulin resistance, and obesity-related health conditions." (PMID 27473122, 2016). "No cure has been found yet for the disease; however, treatment modalities including lifestyle modification, treatment of obesity, oral hypoglycemic agents and insulin sensitizers that reduce insulin resistance are still recommended as first line treatment." (PMID 27754407, 2016). "Expression level of membrane GLUT4 is proposed to evaluate the insulin responsive glucose transporter GLUT4 from intracellular storage sites to the plasma membrane in skeletal muscle that occurs faulty in insulin resistance." (PMID 27271603, 2016). "Participants were categorized as being insulin resistant (IR; SI < 7.8) or insulin sensitive (IS; SI ≥ 7.8) based on Gaussian analysis." (PMID 26766961, 2016). "Type 2 diabetes (T2DM) is a polygenic metabolic disorder characterized by hyperglycemia occurring as a result of impaired insulin secretion or insulin resistance." (PMID 28330327, 2016). "Type I diabetes is a result of insufficient insulin production by the pancreas, whereas type II diabetes is due to the body’s inability to use the insulin that is produced, hence the name insulin resistance is used to refer to type II diabetes." (PMID 27983630, 2016). "Reduction in insulin clearance plays an important role in the compensatory response to insulin resistance." (PMID 27846285, 2016). "A mouse model of severe insulin resistance showed a markedly increased betatrophin level, which acted as a potent mitogen for insulin-producing β-cells." (PMID 27045862, 2016). "The term insulin resistance (IR) was coined in 1936 to describe a metabolic disturbance characterized by decreased cellular responsiveness to insulin signaling in insulin-dependent tissues such as skeletal muscle, liver, and adipose tissue." (PMID 27579182, 2016). "The roles of renin-angiotensin system (RAS) in insulin signaling pathway and insulin resistance have been well documented." (PMID 26682227, 2016).
Insulin resistance (continued). "Our data demonstrated that the Gelam honey extract and quercetin had the best protective effect against hyperglycemia induced oxidative stress by improving the insulin content and insulin resistance." (PMID 27034691, 2016). "Metabolic disorders are characterized by dysregulated insulin response, impaired glucose homeostasis and insulin resistance." (PMID 27180971, 2016). "Whereas impaired fasting glucose reflects predominantly a defect in insulin secretion, impaired glucose tolerance is more closely related to insulin resistance and clinical outcomes." (PMID 26863521, 2016). "Insulin resistance is a well-known feature of obesity, and a low plasma IGF-1 concentration has been reported to be significantly associated with insulin sensitivity." (PMID 27138941, 2016). "Insulin resistance is closely related to inflammation; in prediabetes and type 2 diabetes, cytokines are released that block insulin action, thereby lowering sensitivity and increasing resistance to insulin." (PMID 27811997, 2016). "In utero insulin resistance was first suggested in 2009 in a study on the fetuses of obese women, which included measurements of glucose and insulin concentration in the umbilical cord." (PMID 26758575, 2016). "Due to its ubiquity in the insulin-targeted tissues and its reported role in insulin resistance development, PTP1B is considered a promising therapeutic target for the treatment of DMT2." (PMID 28042834, 2016). "This is supported by evidence of TLR4 signalling which has previously been proposed as playing a role in insulin resistance, being activated in the skeletal muscle of insulin‐resistant human subjects." (PMID 25740151, 2016). "Insulin resistance is induced by the accumulation of lipid metabolites from excess fat in insulin sensitive cells." (PMID 26916435, 2016). "Insulin resistance is a pathological state characterized by an impairment of insulin action in different compartments, including adipose tissue." (PMID 27782064, 2016). "Insulin resistance is a state of glucose homeostasis in which insulin produces a less-than-expected biological effect at the liver, muscle, adipose tissue and other body tissues." (PMID 27193069, 2016). "Taken together, these results clearly indicated an improvement in insulin resistance and insulin sensitivity in db/db mice treated with OFS." (PMID 27941667, 2016). "Since vitamin D effects on NAFLD were tested in T2D patients, we evaluated, as secondary endpoints, the influence of vitamin D treatment on systemic and AT insulin resistance, insulin secretion and glycemic control." (PMID 27353492, 2016). "A common denominator for insulin resistance at the cellular level is decreased activation of Akt by insulin." (PMID 26899548, 2016). "To assess insulin resistance in 6-month old mCaROCCK1 mice, we examined blood glucose values and plasma insulin levels." (PMID 27411515, 2016). "For insulin resistance we found the REACTOME pathway insulin signal attenuation to be genome-wide significant." (PMID 26808494, 2016). "In summary, the results of this study highlight for the first time the in vivo effects of chronic insulin and hCG exposure on the development of uterine insulin resistance." (PMID 27461373, 2016). "It is well known that chronic hyperglycemia due to either decreased insulin secretion or insulin resistance leads to excess free radical generation with a consequent lipid peroxidation, depletion of antioxidants, and enhanced OS in T2DM." (PMID 27298517, 2016). "When exploring the molecular mechanism of insulin resistance and hyperinsulinemia, considerable attention has been paid to the intracellular mechanisms of defective insulin signaling after bonding to the insulin receptor (IR)." (PMID 27101796, 2016). "Overall, the results showed that the HFHC diet worsened metabolic indices and induced insulin resistance partly through transcriptional regulation of the insulin signaling genes." (PMID 26924713, 2016).
Insulin resistance (continued). "Application regimens optimization is required to efficiently overcome pre-existing brain insulin resistance in obese individuals and intranasal insulin delivery is attracting increasing attention as alternative treatment option." (PMID 27589235, 2016). "Supplementation of the HFD with UT significantly lowered fasting glucose and insulin and improved insulin resistance as assessed by HOMA-IR (HFD vs HFD + UT, P < 0.01)." (PMID 26916435, 2016). "To study glucose tolerance and insulin resistance, we performed glucose and insulin tolerance tests before and after HFD feeding." (PMID 27701440, 2016). "In our study, only MTNR1B40 and TCF7L241 involved in impaired insulin secretion, and IRS142 involved in insulin resistance in T2D were significantly associated with GDM." (PMID 27468700, 2016). "Differences are observed in insulin sensitivity in different organs during the development from an insulin resistance stage to a clinically type 2 diabetes stage." (PMID 28933394, 2016). "Consistent with this notion, AdicerKO mice do not benefit from some of the classic metabolic outcomes of DR, such as increased insulin sensitivity and decreased inflammation, and have accelerated age-dependent insulin resistance and premature mortality." (PMID 27241713, 2016). "Fetus will then reduce its insulin secretion and increase peripheral insulin resistance, directing more glucose to the vital organs, including the brain and the heart, and less to insulin-dependent tissues." (PMID 27687906, 2016). "Myoinositol and D-chiro inositol, which are inositol isomers, have been shown to possess insulin-mimetic properties and to improve insulin resistance, especially in women with polycystic ovary syndrome." (PMID 27882052, 2016). "Insulin resistance is the failure of cells to respond to insulin hormone signaling, leading to reduced glucose uptake and hyperglycemia." (PMID 28231100, 2016). "An increase in FFA efflux from adipose tissue to liver can result in insulin resistance in the liver and GH is known to antagonise insulin action by this mean." (PMID 26733412, 2016). "Glucose tolerance test and insulin sensitivity test demonstrated that insulin resistance was significantly ameliorated in Pemt−/− mice compared to Pemt+/+ mice under HFHS chow." (PMID 26883167, 2016). "Skeletal muscle insulin resistance is a common defect in T2DM because nearly 90% of the insulin mediated glucose is taken up by skeletal muscle." (PMID 27941667, 2016). "Nevertheless, the old group presented significant increase in fasting insulin levels, insulin resistance, plasma and hepatic lipid peroxidation, and pronounced steatosis." (PMID 27057272, 2016). "Insulin resistance is a pathophysiological condition in which cells fail to respond to the normal actions of the hormone insulin." (PMID 27101796, 2016). "In the presence of insulin resistance, the pancreas is stimulated to increase insulin secretion to overcome the defect in peripheral glucose uptake and to decrease hepatic glucose production." (PMID 27973438, 2016). "In case that insulin resistance leads to a decrease in insulin promoter activity and thereby biosensor expression we are unable to monitor these cells." (PMID 26899548, 2016). "Pre-clinical and clinical studies have found improvements in insulin resistance and glucose tolerance after blueberry consumption in obese and insulin-resistant rodents and humans." (PMID 27916833, 2016). "Increased cord blood insulin level and HOMA-IR in preterm infants show a risk for developing insulin resistance in preterm newborns." (PMID 27087404, 2016). "Insulin resistance that develops in adipose tissue results in altered ability of insulin signaling cascade to store triglycerides." (PMID 27821850, 2016). "Insulin resistance can mediate cognitive impairment and neurodegeneration as insulin and IGFs can regulate neuronal survival, metabolism, and brain plasticity." (PMID 26881095, 2016).